RB1 (RB transcriptional corepressor 1)
Diseases named in the same sentence as RB1 in open-access papers (continued):
Sharing a sentence is not in itself a finding about the gene and the disease.
tumor (continued). "Notably, Egr1 emerged as a strong tumor suppressor and its knockout resulted in approximately a fivefold increase in tumor size at 20 weeks (two-sample t-test, p < 0.05), exceeding the impact observed with Rb1 loss." (PMID 41705258, 2025). "These mutations may allow for partial function of the RB1 protein, reducing the severity or likelihood of tumor development." (PMID 41009976, 2025). "Indeed, RB1 is classically and unambiguously implicated as a tumor suppressor gene for other cancer types by germline evidence." (PMID 41279109, 2025). "Together these data indicate that RB1 loss increases tumor cell dependence on BCL-XL." (PMID 40436896, 2025). "According to this hypothesis, it was proposed that an RB1 mutation inactivating one of the two alleles (i.e., the ‘first hit’) is necessary to develop a predisposition to malignancy but cannot induce tumor formation by itself." (PMID 40227591, 2025). "Contiguous loss of neighboring genes such as MED4, which is located centromeric to RB1, may modulate RB1 expression or tumor susceptibility." (PMID 41009976, 2025). "RB1, a well-known tumor suppressor, encodes the retinoblastoma protein (pRb)." (PMID 39796173, 2025). "Some of these may act as cooperating mutations in RB1-deficient tumors or influence tumor progression, mostly in cases with chromosomal instability." (PMID 41009976, 2025). "Tumor formation occurs when the second RB1 allele is inactivated in retinal cells." (PMID 41002743, 2025). "Additionally, the loss of one copy of Chr 13, where RB1 is located, was observed in both tumor components." (PMID 40600748, 2025). "Tumor tissue, if available, can also be tested for RB1 mutations and deletions/duplications." (PMID 41009976, 2025). "In addition, one primary tumor (A12) exhibited a subclonal RB1 mutation [cancer cell fraction (CCF) 71%] with a corresponding subclonal loss of pRb expression by IHC in ∼70% of the tumor cross-sectional area." (PMID 39185963, 2025). "To the contrary and consistent with our observations with the 16S rRNA profiling data, we observed significantly more predicted functions shared between TRAMP-C2 tumours-associated microbiota and Pten−/−; Rb1−/−-related microbiota compared to Pten−/−; Rb1+/+-related microbiota." (PMID 38654015, 2024). "This suggests that inhibition of PI3K pathway may represent a therapeutic target for tumours harbouring Rb1 mutations." (PMID 38785992, 2024). "This subset of tme-lncRNAs was correlated with a previously published tumor-intrinsic transcriptomic signature of RB1 loss, suggesting that proliferative pathways in cancer cells may lead to concomitant changes in the immune microenvironment." (PMID 38396008, 2024). "In the present case, these two intronic RB1 variants may result in the production of a dysfunctional Rb protein that allows for arrested differentiation of the tumor." (PMID 39493168, 2024). "Interestingly MYC and RB1 were the most frequently altered genes that were associated significantly with a lower abundance of CD8+ T-cell infiltrates across different tumor types." (PMID 38398121, 2024). "Interestingly, only CU-PC01 PDX tumours at P1 and P7 carried an RB1 missense mutation within the C-terminal domain (P793S) that is expected to be tolerated." (PMID 38667288, 2024).
tumor (continued). "Tumors with complete absence of CD8+ TILs were the least frequent in gBRCAvar with RB1 loss (4.1%) compared with the other groups (13.8% of gBRCAvar with retained RB1 tumor expression, 14.6% of gBRCAwt with RB1 tumor loss, and 18.8% of gBRCAwt with retained RB1 tumor expression)." (PMID 38837893, 2024). "In line with the results from previous studies, tumor sequencing detected biallelic somatic mutations in RB1 in 78% (7/9) of patients, whose siblings can be exempted from surveillance, thus sparing them 13 examinations under anesthesia during their first four years of life." (PMID 38803632, 2024). "However, the MYCN-induced RB1-proficient phenotype was consistently more immature and less differentiated with faster tumour progression than that of the RB1-deficient." (PMID 37606819, 2024). "The characterization of RB1 causal variants in the tumour can also aid in the detection of low-level germline mosaicism, due to the increased sensitivity of targeted variant analysis compared to gene screening, when the pathogenic variants are unknown." (PMID 38672657, 2024). "Notably, loss of Rb1 has been showed to cooperate with PTEN loss to initiate retinoblastoma tumours in mice." (PMID 38785992, 2024). "Aberrations within the RB1 gene, encompassing both deleterious mutations and deletions, culminate in the abrogation of functional pRB protein, which initiates an unrestrained cell proliferation, resulting in tumour formation and ultimately leading to RB." (PMID 38975183, 2024). "Changes in SV40 large T antigen-driven tumour-associated microbiota were more resembling with Pten−/−; Rb1−/−-related microbiota than Pten−/−; Rb1+/+, again supporting that Rb1 loss of function is prompting the growth of larger tumours resulting in more significant gut microbiota alterations." (PMID 38654015, 2024). "Moreover, the tumor cells showed near-complete loss of retinoblastoma (RB1) expression (<1% of cells positive)." (PMID 37401932, 2023). "Among the tumor cell-related factors, RB1 loss has been linked to an accumulation of MDSC." (PMID 37370686, 2023). "To test whether ferroptosis could represent a cancer vulnerability elicited by RB1 deficiency, we carried out in vivo preclinical studies of ferroptosis-inducing therapy in two distinct but complementary tumor model systems." (PMID 36928314, 2023). "Such increased sensitivity to chemotherapy suggests that RB1 loss might predispose tumor cells to specific cell death pathways." (PMID 37183818, 2023). "In case 02, the large tumor area displaying GA for the three tested genes also displayed RB1 loss." (PMID 37610648, 2023). "Analysis of tumor samples and circulating tumor DNA (ctDNA) of patients receiving CDK4/6i plus ET have shown loss of RB1 at baseline or with treatment is associated with shorter progression-free survival (PFS), although such alterations appear uncommon, occurring in < 10% of resistant samples." (PMID 37475004, 2023).
tumor (continued). "RB is a tumor suppressor gene encoding the retinoblastoma susceptibility protein 1 (RB1)." (PMID 36674870, 2023). "RB1 mutation may lead to loss of the tumor suppressor function of the RB1 protein, thus promoting excessive cell proliferation, avoiding apoptosis, delaying cell senescence, and participating in the occurrence and development of tumors." (PMID 36737820, 2023). "The majority of patients present with unilateral tumor and have a somatic pathogenic RB1 mutation." (PMID 37658463, 2023). "In addition, mutations in CDKN2A and RB1 are enriched in tumors with poor prognosis, suggesting a role of p21 pathway inactivation in tumor aggressiveness." (PMID 36765775, 2023). "Therefore, one possibility is that in tumor cells with loss of RB1 function, IFN-β signaling reduces the phosphorylation of p107 to form p107/E2F or other p107 complexes to induce a p107-mediated suppression of the S phase progression." (PMID 37182173, 2023). "Additionally, analysis of circulating tumor DNA (ctDNA) from BC patients that had disease progression on CDK4/6i revealed the acquisition of RB1 loss-of-function mutations in some of these patients." (PMID 37835528, 2023). "Tumor development is associated with the retinoblastoma susceptibility gene (RB1), a recessive tumor suppressor gene involved in cell growth and development, and it is reported that it only occurs when both alleles of RB1 are lost or undergo deletion, inactivation, or mutation." (PMID 38001596, 2023). "By applying a hybrid capture targeted sequencing approach, we not only systematically profile SNVs along the RB1 gene, but we also observe high intra-patient concordance of SCNAs between respective AH and tumor samples and confirm all germline RB1 variants in each bioanalyte." (PMID 37239954, 2023). "RB1 is a tumor-suppressor gene and encodes pRB, a key regulator of the cell cycle." (PMID 36497448, 2022). "Mutations in Rb1 are associated with more aggressive tumours." (PMID 36499267, 2022). "RB1 (retinoblastoma) is a tumor suppressor gene whose loss drives tumorigenesis in limited types of cancer, but importantly, its function is often suppressed during tumor progression." (PMID 35625825, 2022). "Nevertheless, potential explanations that lie behind YAP1 loss might be related to tumor microenvironment, RB1 mutation status, and sensitivity to standard‐of‐care CHT." (PMID 35489038, 2022). "Rb1 inactivation triggers increased genomic instability, which can subsequently lead to the generation of proteins with altered sequences that can serve as tumor-associated or tumor-specific antigens, which would be presented on the surface of cancer cells." (PMID 35267571, 2022). "We asked whether the presentation of tumor focality in RB diagnosed at the first visit is related to the status of germline RB1 mutation." (PMID 36173648, 2022). "Retinoblastoma susceptibility gene (RB1) is the first identified tumour suppressor gene." (PMID 35650644, 2022). "In 98% of cases, the tumor is caused by inactivation of the RB1 gene." (PMID 35565295, 2022). "Because of its roles in chromatin regulation and tumor suppression, we investigated whether RB1 could also influence UV susceptibility, a mechanism distinct from its previously characterized roles." (PMID 34983823, 2022). "CNA-containing genes included oncogenes showing copy number gain such as Yap1, Braf, Foxo1, and Akt3 and tumor suppressors with copy number loss such as Rb1, which may favor tumor growth." (PMID 36376321, 2022).
tumor (continued). "When comparing the mutations identified in the NSCLC and SCLC groups, we observed that RB1 was depicted with a higher number of different mutations in tumor samples and this gene was altered in a higher number of patients in the SCLC group; this result was consistent with the TCGA data analysis." (PMID 35330454, 2022). "Comprehensive genomic tumor profiling identified mutations in RB1 p.R255 and MUTYH p.G382D." (PMID 35821675, 2022). "Notably, this region hosts the RB1 locus, codifying a crucial tumor-suppressor whose loss is associated with resistance to anti-CDK4/6 therapies in ER-positive BC." (PMID 36010918, 2022). "Based on this, we do not state that the candidates that did not pass through the additional screens are not valid targets in RB1-deficient cells, we only state that the candidates that passed through all filters would more likely kill RB1-deficient cells in highly heterogeneous tumor cells." (PMID 33591981, 2021). "It indicated that the frequency of RB1 mutation might play a promising role in monitoring tumor recurrence." (PMID 34177933, 2021). "Seven tumours remained with unconfirmed biallelic RB1 mutations." (PMID 33670346, 2021). "RB1 is a tumor suppressor that is often mutated in multiple different tumors and finding new therapeutic targets to specifically kill RB1-deficient cells could potentially lead to a targeted therapy for these tumors." (PMID 33591981, 2021). "These evidences demonstrated that high RB1 mutation and tumor-infiltrating macrophages may account for the poor prognosis in high-risk group." (PMID 34490263, 2021). "Given the close association of MRPS31 with RB1, a core tumor suppressor, we questioned whether MRPS31 loss could substantially contribute to HCC development rather than be an epiphenomenon." (PMID 34772924, 2021). "Two pathogenic RB1 mutations were identified in each of the tumor samples." (PMID 34003213, 2021). "The authors therefore suggest that a modified tumour fraction calculation based on RB1 variants, which >99% patients carry, may be preferable." (PMID 33805427, 2021). "Moreover, RB1 is a known tumor-suppressor gene, and the loss of RB1 is the main mechanism of acquired resistance in HCC." (PMID 33686959, 2021). "This choice is justified by the following: (i) the role of class IIa and of their partners in this tumor is well characterized and (ii) mutations in two key elements of the senescent pathway, RB1 and CDKN2A, in LMS are mutually exclusive and strongly associate with patient survival." (PMID 33966634, 2021). "In this form of the disease, a germline mutation of one of the RB1 alleles predisposes to tumor development and determines familial transmission, while a somatic mutation of the other allele is acquired in utero or in early childhood and triggers tumorigenesis." (PMID 34680218, 2021). "Additionally, in one case, tumours from both the left and right eye were available from a paediatric patient with a germline RB1 mutation providing an opportunity to determine phylogenetic relatedness between bilateral tumours in germline mutation carriers." (PMID 33670346, 2021). "We hypothesize that this bicalutamide-pretreated tumor had relative enzalutamide resistance associated with baseline RB1 loss and quickly developed increased RTK signaling and suppressed apoptotic response (MCL1 gains) on enzalutamide." (PMID 34568716, 2021). "iAMP21 tumours were characterised by excess RB1 deletion (40%) and IL7R mutation (20%)." (PMID 34753926, 2021).
tumor (continued). "Therefore, loss of LATS2 impairs functions of DREAM complex, cooperating with RB1 loss to promote tumor development." (PMID 34359636, 2021). "Nevertheless, loss of RB1 tumor suppressor activity is critical for pNET development." (PMID 34680266, 2021). "Notably, the low-risk tumor groups have significantly lower rates of FGFR3 mutation while the overall mutation rates of RB1 appeared to be higher in the high-risk subgroup." (PMID 34490263, 2021). "In our data, we focused on tumors with mutations in RB1 but CN-LOH is a mechanism that may affect different tumor suppressor genes in other tumor types." (PMID 33466343, 2021). "In cultured cells, including embryonic fibroblasts and thyroid C cells, K-Ras and N-Ras are activated 5~10 times greater following RB1 loss, and this may promote or suppress tumor development in a highly context-dependent manner." (PMID 34359636, 2021). "Understanding of the molecular mechanisms driving RB tumor progression following tumor‐initiating mutations in RB1 gene has been a subject of intense research since the discovery of RB1 tumor suppressor gene and its alterations as causative genetic lesions for RB development." (PMID 32840881, 2021). "Additionally, there is a significant association between tumor RB1 and viral LT antigen expression in MCPyV+ MCCs." (PMID 34208339, 2021). "Moreover, relative to the primary tumor, it maintained additional potent oncogenic alterations found in the metastases, including RB1 loss." (PMID 34568716, 2021). "However, in the PALOMA-3 randomized phase III trial, the circulating tumor DNA sequencing from patients showed that Rb1 mutations occurred only in 6 of 127 (4.7%) patients." (PMID 34123801, 2021). "Because RB tumors (with few exceptions) harbor somatic RB1 mutations, an RB1-based VAF pipeline may provide a better measurement of tumor burden and therapeutic response." (PMID 33805776, 2021). "Considering the key tumor-suppressive role of RB, the dependence of MRPS31 loss on RB1 deletion prompted us to ask whether MRPS31 loss is just an epiphenomenon during HCC development." (PMID 34772924, 2021). "Both RB1 mutations were detected by clinical screening in one tumour (PD34256)." (PMID 33670346, 2021). "REC classes identify genotype-phenotype relationships and, therefore, this classification framework may serve as a tool to develop tailored tumor screening programs depending on the type of RB1 variant." (PMID 33807189, 2021). "It is characterized by biallelic inactivation of the RB Transcriptional Corepressor 1 gene (RB1) which encodes the retinoblastoma protein (RB1), a well-established tumor suppressor that interacts with the E2F family of transcription factors to negatively regulate the cell cycle." (PMID 33827698, 2021). "While this likely indicates that a germline mutation is not present, the test is formally considered non‐informative since the tumor's RB1 mutation is unknown and the absence cannot be confirmed in the blood." (PMID 32633890, 2020).